TRPA1 (transient receptor potential cation channel subfamily A member 1)
Diseases named in the same sentence as TRPA1 in open-access papers (continued):
Sharing a sentence is not in itself a finding about the gene and the disease.
diabetes (continued). "The present study investigated the effects of Andaliman (Z. acanthopodium) fruit extract on biological markers relevant to diabetes management, namely BGL, TNF-α, and TRPA-1." (PMID 39101085, 2024). "TRPA1 is also sensitised in rat DRG immortalised neurons (50B11) in high-glucose conditions in vitro and in animal models of diabetes." (PMID 29930087, 2018). "However, intrathecal injections of the TRPA1 antagonist CHEM-5861528 have been found to reverse mechanical allodynia in streptozotocin-induced diabetic rats and may prevent diabetes-induced loss of nociceptor nerve endings in the skin." (PMID 25640188, 2015). "We examined skin sections from Trpa1+/+ and Trpa1−/− mice treated with the GLO-1 inhibitor or vehicle for 2 weeks to assess whether the hypersensitivities produced by inhibition of GLO-1 were accompanied by a loss of IENFs, similar to that seen in mouse models of diabetes." (PMID 24167592, 2013). "Estrogen metabolites and certain dietary compounds may also activate TRPA1 to promote insulin secretion and GLP-1 release from intestinal L cells, which may be an appropriate method for diabetes management." (PMID 39273183, 2024). "In cell lines, differentiation and inflammation were tested, which does not fully exclude a TRPA1 expression in pathophysiological states as, for example, diabetes or hypertrophy." (PMID 33819369, 2021). "TRPA1 and TRPV1 are important molecules in the sensitisation of peripheral nociceptive afferents, and TRPV1 is directly sensitised by high-glucose conditions in sensory neurons and during diabetes in vivo." (PMID 29930087, 2018). "In line with this, diabetes mellitus produces endogenous substances, such as methylglyoxal and 4-hydroxy-nonenal that are TRPA1 agonists." (PMID 30388732, 2018). "Furthermore, disruption of either TRPA1 or AC1 attenuated MG-evoked hyperalgesia in the current results, and is sufficient to reduce hyperalgesia in rodent models of diabetes where MG is elevated." (PMID 29270106, 2017). "However, another study demonstrated that the deleterious effects of streptozotocin (a compound used for experimental diabetes induction) on β-cells are independent of TRPA1 activation." (PMID 35455971, 2022). "Indeed, preliminary data from our laboratory clearly indicate that as a function of diabetes, guanfacine suppresses the increase in mRNA expression of TRPV1 and TRPA1 in several regions of the central nervous system including pons, LSSC, and DRG (unpublished data)." (PMID 36297581, 2022). "Thus, it remains to be determined whether cross-desensitization or cross-activation between TRPA1 and TRPV1 would prevail in regulating TRPV1 current kinetics in diabetes." (PMID 30795543, 2019). "In the early phase of diabetes, in contrast, endogenous TRPA1 agonists may have a key role in the induction of the first symptoms and degenerative signs of PDN through action on a subpopulation of TRPA1-expressing nociceptive nerve fibers." (PMID 30388732, 2018). "With prolongation of diabetes, metabolic mechanisms are expected to exert a major role in PDN leading to a loss of various types of nerve fibers and mechanical hyposensitivity that are independent of TRPA1, as demonstrated in a recent mouse study." (PMID 30388732, 2018). "We found that experimental diabetes increased TRPC6, but not TRPV1 nor TRPA1, protein expression in DRG." (PMID 30602386, 2019). "Moreover, TRPA1 can be activated by oxidative stress and glucose metabolism by-products, such as 4-hydroxy-2-nonenal (4-HNE) and methylglyoxal, which are elevated in diabetes, contributing to hyperalgesia." (PMID 37781093, 2023).
melanoma (22 papers, 2014 to 2026). A malignant, usually aggressive tumor composed of atypical, neoplastic melanocytes. "Although TRPA1 expression has been reported in melanoma cell lines, and oxidative stress has been associated with melanocytic transformation, their role in melanoma remains poorly known." (PMID 34831352, 2021). "Solar ultraviolet radiation, a major risk factor for melanoma, elicits melanin formation via TRPA1 in melanocytes." (PMID 34831352, 2021). "Results indicate that increased peritumoral and intratumoral M2 TAM are positively associated with 4-HNE levels, and that TRPA1 stimulated by ROS amplifies the oxidative stress signal in cultured melanoma cells." (PMID 34831352, 2021). "The expression of TRPA1 in two different melanoma cell lines was associated with their ability to evoke a calcium response by channel agonists AITC and H2O2." (PMID 34831352, 2021). "TRPA1 appears to be implicated in mechanistic processes in various immunological inflammatory diseases and cancers of the skin, such as atopic and allergic contact dermatitis, psoriasis, bullous pemphigoid, cutaneous T-cell lymphoma, and melanoma." (PMID 33802836, 2021). "For example, although TRPM1 (transient receptor potential cation channel subfamily M member 1) is expressed in melanocytes mediating melanin production in melanoma, TRPA1 promotes tumour progression and invasiveness and is linked to a more aggressive disease phenotype." (PMID 31003534, 2019). "In vitro experiments on melanoma cell lines have shown that TRPA1 activation is associated with the release of H2O2, an observation in line with previous findings that have indicated the channel as an oxidative stress sensor and amplifier, a function that might affect tumor cells and proliferation." (PMID 37892239, 2023). "Exposure to alkaline pHe (8.1) or allyl isothiocyanate (AITC), a TRPA1 agonist, significantly reduced melanoma cell viability." (PMID 42121861, 2026). "Here, we report that transient receptor potential ankyrin 1 (TRPA1) functions as an alkaline sensor and mediator of cell death in melanoma cells." (PMID 42121861, 2026). "In cancers, especially breast cancer and melanoma, TRPA1 affects pain and tumor progression through oxidative stress responses." (PMID 39273183, 2024). "TRPA1, which is highly sensitive to oxidants, is functionally expressed in melanoma cells and can be activated by H2O2 to produce calcium-dependent responses." (PMID 39273183, 2024). "TRPA1 activation in melanoma cells involves canonical ROS-neutralization mechanisms and non-canonical oxidative stress defense, leading to cancer progression through anti-apoptotic pathways." (PMID 39273183, 2024). "A recent investigation demonstrated that H2O2-dependent TRPA1 activation can amplify oxidative stress in melanoma cell lines." (PMID 37174661, 2023). "In a melanoma orthotopic mouse model, Trpa1−/− mice showed higher CD8+ T-cell activation and tumor infiltration as well as lower tumor progression than Trpa1+/+ animals, indicating that TRPA1 diminishes CD8+ T-cell cytotoxicity." (PMID 37762011, 2023). "De Logu and collaborators demonstrated that H2O2 evoked a TRPA1-dependent Ca2+ response in two distinct melanoma cell lines (SK-MEL-28 and WM266-4), thus promoting anti-apoptotic and pro-oncogenic programs." (PMID 36614330, 2023). "In samples of skin lesion and melanoma, the presence of TRPA1 has been correlated with a progressive increase in oxidative stress and melanocytic transformation, as well as tumor severity." (PMID 37892239, 2023). "4-HNE has recently been shown to stimulate TRPA1-mediated Ca2+ influx in several cell types, including melanoma cell lines." (PMID 37393347, 2023). "In this line, another study reports that mice with TRPA1 ubiquitous deletion show an increased cytotoxic lymphocyte response against melanoma cells and, consequently, lower tumor progression." (PMID 37762011, 2023).
melanoma (continued). "In a mouse model of cancer induced by the subcutaneous inoculation of melanoma B16-F10 cells, neuronal TRPA1 has been proposed to mediate mechanical and cold hypersensitivity and thigmotaxis behavior." (PMID 37892239, 2023). "TRPA1 is highly sensitive to 4-HNE and 4-HNE-induced TRPA1 activation has been reported in melanoma cell lines." (PMID 37393347, 2023). "To address this question, we evaluated the participation of the TRPA1 channel in the immune response against melanoma tumor progression in a model of murine melanoma." (PMID 34041030, 2021). "The expression of TRPA1, a major chemosensory receptor for ROS, was evaluated in tissue samples of dermal and dysplastic nevi and pT1 and pT4 malignant melanomas." (PMID 34831352, 2021). "In dermal and dysplastic nevi, as well as in melanoma cells, TRPA1 immunoreactivity was comparable and mostly confined to the cell cytoplasm and peripheral (plasma or cell membrane) membrane without nuclear pattern." (PMID 34831352, 2021). "In TRPA1 low primary melanoma increased frequency of activated natural killer, resting dendritic, and eosinophils were found compared to TRPA1 high tumors." (PMID 34041030, 2021). "In a second phase, TRPA1, in melanoma cells targeted by ROS from MΦs, amplifies the oxidative stress in TME." (PMID 34831352, 2021). "Hydrogen peroxide (H2O2) evoked a TRPA1-dependent calcium response in two distinct melanoma cell lines (SK-MEL-28 and WM266-4)." (PMID 34831352, 2021). "In order to fill this gap, we used a model in which Trpa1+/+ and Trpa1-/- mice were inoculated with B16-F10 melanoma cells to understand CD8+ T activation and tumor progression." (PMID 34041030, 2021). "Indeed, our results show that Xenopus melanophores express multiple and similar TRP channels, including Trpm8,15 Trpa1, Trpv1, Trpv2, and Trpv4, to those detected in mammalian melanocytes and melanoma cells." (PMID 40978134, 2025). "The TRPA1 protein has been identified in benign human skin lesions (dermal melanocytic nevi and dysplastic nevi), in cutaneous thin (pT1) and thick (pT4) melanomas, and in two different melanoma cell lines (SK-MEL-28 and WM266-4)." (PMID 37892239, 2023). "In addition, genetic (via a selective small interfering RNA) and pharmacological (via A967079) blockade of TRPA1 suppressed H2O2-evoked intracellular Ca2+ signals in the human melanoma cell lines WM266-4 and SK-MEL-28." (PMID 37174661, 2023). "Furthermore, TRPA1 activation by H2O2 has been shown to evoke additional H2O2 release in melanoma cell lines that further amplify the oxidative stress." (PMID 37325677, 2023). "A recent investigation suggested that H2O2-induced Ca2+ entry via TRPA1 could also engage an antioxidant defense program in melanoma, which presents a rather high oxidative stress in the tumor microenvironment." (PMID 37174661, 2023). "In addition, the expression of TRPA1 has been observed in different cancer cells, including pancreatic adenocarcinoma and melanoma cells." (PMID 37892239, 2023). "Here, we asked whether TRPA1 could increase ROS production in the two different melanoma cell lines." (PMID 34831352, 2021). "This study provides a novel evidence that TRPA1 could represent an important modulator of immune cells and a putative new pharmacological target in melanoma treatment." (PMID 34041030, 2021). "ROS release from infiltrating M2 MΦs may target TRPA1-expressing melanoma cells to amplify the oxidative stress signal that affects tumor cell survival and proliferation." (PMID 34831352, 2021). "Our finding that H2O2 elicits a TRPA1-dependent calcium response in melanoma cells extends to melanoma the hypothesis that TRPA1 promotes antiapoptotic pro-oncogenic programs." (PMID 34831352, 2021). "TRPA1, which exhibits the highest sensitivity to oxidants due to the presence of hyperreactive cysteines in cytoplasmic domains, previously and in this study, has been found functionally expressed in melanoma cells." (PMID 34831352, 2021).
melanoma (continued). "Thus, a functional TRPA1 channel expressed by melanoma cells is targeted by ROS to amplify the oxidative stress signal." (PMID 34831352, 2021). "If true, this could serve as the mechanistic explanation as to why we observed such a great degree of delay in tumor progression in Trpa1- / - mice inoculated with melanoma cells." (PMID 34041030, 2021). "In addition, we studied the expression of TRPA1 in two different melanoma cell lines and its ability to sense and amplify the oxidative stress signal." (PMID 34831352, 2021). "However, the implication of TRPA1 in the signaling pathway, which from infiltrating MΦs results in increased oxidative stress and its amplification in melanoma, is poorly known." (PMID 34831352, 2021). "Certain compounds such as TRPA1 activators like cinnamaldehyde and allyl isothiocyanate could reduce the proliferation of melanoma cells." (PMID 30881453, 2019). "Several human melanoma-derived cell lines were also shown to express TRPA1 and to exhibit calcium responses to TRPA1 agonists that could be suppressed by a TRPA1 selective antagonist." (PMID 27983625, 2016). "Recent studies have shown TRPA1 agonists to promote cell survival at low levels, but equally, may inhibit proliferation of melanoma cells and actually promote pro-proliferation gene expression patterns within human keratinocytes." (PMID 25505598, 2014). "Importantly, TRPA1 activation in melanoma cells amplifies oxidative stress signaling." (PMID 39273183, 2024). "The modulatory role of TRPA1 channel may also affect other types of immune system and healthy cells in the tumor microenviroment, and therefore, may result in exciting putative pharmacological targets in melanoma treatment." (PMID 34041030, 2021). "However, in the same study, TRPA1 agonist-induced changes in cellular proliferation were insensitive to this same antagonist, potentially arguing against a clear role for this channel as a target of melanoma therapy." (PMID 27983625, 2016). "Transient receptor potential ankyrin 1 (TRPA1), belonging to a subgroup of TRP channels, also appears to contribute to melanoma progression." (PMID 36614330, 2023). "Recent studies have reported that TRPM8 and TRPA1 exhibit abnormal expression in melanoma cell lines, and functional TRPV1, TRPM8, and TRPA1 have been found in malignant uveal melanoma tissues and cell lines." (PMID 34831352, 2021). "We found that TRPV2/4, TRPA1, and TRPM8 exhibited ectopic distribution both in melanocytes and melanoma cells." (PMID 30881453, 2019). "In the present study, six thermo-TRPs including four heat sensors of TRPV1/2/3/4 and two cold sensors of TRPA1 and TRPM8 have been investigated among human melanocytes and melanoma cells." (PMID 30881453, 2019). "In the present study, six thermo-TRPs including TRPV1/2/3/4, TRPA1, and TRPM8 were examined in human primary melanocytes and melanoma cells." (PMID 30881453, 2019). "TRPA1-mediated NK activation determines the upregulation of CD107 and NKp44 and also increases granzyme expression and the capacity of NK cells to kill both K562 cells and melanoma cell lines." (PMID 37834182, 2023). "Finally, the expression and functional activity of TRPA1 was evaluated in two different melanoma cell lines, SK-MEL-28 (malignant melanoma) and WM266-4 (derived from a metastatic site of a malignant melanoma) cells." (PMID 34831352, 2021). "Thus, TRPA1 and PLD1 are potential targets for therapeutic intervention in melanoma." (PMID 42121861, 2026). "Therefore, activation of TRPA1 by H2O2 may promote an anti-apoptotic, pro-oncogenic program in melanoma." (PMID 39273183, 2024). "Furthermore, TRPA1 was found to be functionally expressed in various human malignant melanoma cell lines but, at the same time, was not critical for an impaired proliferation caused after exposure of these cells to AITC (25–400 μM)." (PMID 31003534, 2019).
ischemia (21 papers, 2016 to 2024). A hypoperfusion of the BLOOD through an organ or tissue caused by a PATHOLOGIC CONSTRICTION or obstruction of its BLOOD VESSELS, or an absence of BLOOD CIRCULATION. "Our data, however, would suggest that BCAS 14d and 28d mouse brains showed evidence of an anti-inflammatory or neuroprotective state as shown by a significant increase in the expression of S100A10, IL-10, Nrf2, and TRPA1, all of which have been linked to ischemia-induced neuroprotection." (PMID 40895091, 2024). "The functional inhibition of TRPA1 located on oligodendrocytes may decrease the myelin damage caused by ischemia." (PMID 34959735, 2021). "In conclusion, our data suggest that post-ischemic painful dysesthesia following a transient compressive hindlimb ischemia/reperfusion is caused by ROS-evoked activation of TRPA1 sensitised by hypoxia through inhibition of PHD-mediated hydroxylation of the TRPA1 Pro394 residue." (PMID 26983498, 2016). "Consistent with the notion that in our model, BCAS showed increased expression of anti-inflammatory markers, we looked for two other putative anti-inflammatory markers known to be affected by ischemia, namely, TRPA1 ion channels and Nrf2." (PMID 40895091, 2024). "Such substances are released during ischemia and it has been described that TRPA1 acts as a sensor of hypoxia, as well as for reactive oxygen and nitrogen species." (PMID 36768836, 2023). "Another study exclusively contains in vitro experiments with isolated cardiomyocytes and comes to the conclusion that activation of cardiomyocyte TRPA1 promotes survival in ischemia." (PMID 36768836, 2023). "Time points ‘Early’ and ‘Late’ were performed to be able to differentiate between TRPA1 inhibition during reperfusion (‘Early’ and ‘Late’) compared to a potential additional effect when the antagonist is also present during ischemia (only ‘Early’)." (PMID 36768836, 2023). "It is known that myelin damage can be receptor‐mediated and recently oligodendrocytes have been shown to express Ca2+‐permeable Transient Receptor Potential Ankyrin‐1 (TRPA1) channels, whose activation can result in myelin damage in ischemia." (PMID 36762504, 2023). "Blocking oligodendrocyte TRPA1 reduces post-stroke energy deprivation and reduces myelin damage during ischemia." (PMID 36875034, 2023). "Ischemia-induced retinal cell death results from the release of lactate dehydrogenase (LDH) due to oxygen–glucose deprivation (OGD) and inhibition of TRPA1 can be a therapeutic potential for ischemia-induced retinal damage by blocking LDH release due to OGD." (PMID 36986445, 2023). "Nevertheless, while we were conducting the present study, further reports were published implying such a direct effect of TRPA1 on cardiomyocytes in ischemia." (PMID 36768836, 2023). "Intriguingly, it was recently suggested that transient receptor potential ankyrin 1 (TRPA1) is involved in chronic post-ischemia pain, a CRPS model." (PMID 35069559, 2021). "These facts suggest TRPA1 as a potential principal target to reduce ischemia-induced inflammation and pain." (PMID 35069559, 2021). "Collectively, these data indicate that TRPA1 channels in the cerebral endothelium are vital sensors of acute hypoxia and mediate protective vasodilation in brain areas affected by ischemia." (PMID 34064835, 2021). "To recapitulate relevant pathophysiological pO2 levels consistent with ischemia-induced peri-infarct pO2, we investigated the effects of a pO2 of ~10-15 mmHg on TRPA1 activity." (PMID 34064835, 2021). "Here, we investigated the role of TRPA1 in retinal damage evoked by ischemia (1 hour) and reperfusion (I/R) in mice." (PMID 32801314, 2020). "Given the extensive uncertainty afforded by the bimodal regulatory nature of NO in cardiac tissue, we subsequently assessed the extent to which TRPA1-induced NO production is involved in ischemia-induced CM cell death." (PMID 31161862, 2019).